ELP4 (elongator acetyltransferase complex subunit 4)
Description:
Component of the elongator complex which is required for multiple tRNA modifications, including mcm5U (5-methoxycarbonylmethyl uridine), mcm5s2U (5-methoxycarbonylmethyl-2-thiouridine), and ncm5U (5-carbamoylmethyl uridine). The elongator complex catalyzes the formation of carboxymethyluridine in the wobble base at position 34 in tRNAs.
Synonyms: hELP4; C11orf19; PAXNEB; AN; AN2; PAX6NEB; dJ68P15A.1
Tractability: PROTAC: ubiquitination databases record sites on it; its protein half-life has been measured.
Gene: Protein-coding gene on chromosome 11 (31,509,755 to 31,790,324, forward strand). Ensembl gene ENSG00000109911.
Subcellular location: Cytoplasm; Nucleus
Subcellular location (Human Protein Atlas): Nucleoplasm
Pathways (Reactome):
Chromatin organization: HATs acetylate histones
Gene Ontology:
Molecular function: protein binding
Biological process: regulation of transcription by RNA polymerase II; regulation of translation; tRNA wobble uridine modification
Cellular component: cytoplasm; elongator holoenzyme complex; nucleoplasm; nucleus; transcription elongation factor complex
Genetic constraint (gnomAD): Loss-of-function variants: 30 observed, 29.56 expected, observed/expected ratio (o/e) 1.01, 90% interval 0.76 to 1.38. The upper end of that interval is the gene's LOEUF score, 1.38, which puts it in group 5 of 6, group 1 being the genes least tolerant of losing a copy. Missense variants: 370 observed, 371.24 expected, observed/expected ratio (o/e) 1, 90% interval 0.92 to 1.09. Synonymous variants: 156 observed, 142.22 expected, observed/expected ratio (o/e) 1.1, 90% interval 0.96 to 1.25.
Homologues: Orthologues: chimpanzee ELP4 (91% identical), macaque DNAJC24 (83% identical), dog ELP4 (81% identical), rabbit ELP4 (80% identical), rat AABR07053185.1 (78% identical), mouse Elp4 (77% identical), guinea pig ELP4 (76% identical), pig ELP4 (73% identical), rat Elp4-ps1 (70% identical), tropical clawed frog elp4 (55% identical), zebrafish elp4 (49% identical), Drosophila melanogaster Elp4 (30% identical), and 1 more.
Diseases named in the same sentence as ELP4 in open-access papers:
ELP4 is named in the same sentence as 29 diseases in open-access papers, as found by Europe PMC text mining. Sharing a sentence is not in itself a finding about the gene and the disease. The quoted sentences say what the papers report.
aniridia (9 papers, 2011 to 2026). Aniridia is a congenital ocular malformation characterized by the complete or partial absence of the iris. "In this study, the novel 517 kb heterozygous deletion (chr11:31,139,019–31,655,997) downstream of PAX6 containing four annotated genes, DCDC1, DNAJC24, IMMP1L, and ELP4, is likely to be the cause of the familial aniridia in this Chinese family." (PMID 37752489, 2023). "Precise mapping of the breakpoints is very important in accurate molecular diagnosis of children with aniridia in order to determine not only the risk of developing Wilms tumor but also neurodevelopmental disorder (deletion of the ELP4 gene)." (PMID 29460221, 2018). "This turns out to be of particular interest by analyzing one of the VUS identified in this cohort, i.e., a 260.8 kb deletion assessed in a patient with familial aniridia (A114) involving part of the ELP4 gene (int2-3 to int9-10)." (PMID 38459225, 2024). "Isolated aniridia can be caused by point mutations in the PAX6 gene (aniridia type 1), ELP4 gene (chromosome 11p13) (aniridia type 2), and TRIM44 gene (chromosome 11p13) (aniridia type 3)." (PMID 39600756, 2024). "A deletion involving most of the coding region of the ELP4 gene, from intron 2–3 to intron 9–10 (arr[GRCh37]11p13(31541660_31802443)x1), was assessed in a patient with bilateral aniridia, nystagmus, posterior polar cataract, and bilateral corneal dystrophy (A114)." (PMID 38459225, 2024). "Taken together, a 517 kb heterozygous deletion containing four annotated genes, DCDC1, DNAJC24, IMMP1L, and ELP4, was identified in this Chinese family with congenital aniridia, suggesting that transcription-regulating elements in the deleted region are required for the expression of PAX6." (PMID 37752489, 2023). "Recently a ~406 kb heterozygous genomic deletion containing four annotated genes (DCDC1, DNAJC24, IMMP1L, and ELP4) was found in patients with aniridia; apparently the gene contents in this deletion are the same as the 566 kb heterozygous deletion in the family we report here." (PMID 21321669, 2011). "Only in two patients with aniridia, deletions downstream of the PAX6 gene including the ELP4 gene affecting the entire critical region were identified." (PMID 29460221, 2018). "Additionally, in a familial case of isolated aniridia (ANIRIDIA-052), the WAGR-array found a microdeletion of 63 Kb affecting exons 5a to 13 of PAX6, and also partially of the downstream ELP4 gene." (PMID 28231309, 2017). "Two aniridia pedigrees have also been described in which deletion in the ELP4 gene region, not involving PAX6, was present in all subjects with aniridia but not in the investigated normal relatives." (PMID 21321669, 2011).
Rolandic epilepsy (7 papers, 2011 to 2023). "ELP4 is implicated in rolandic epilepsy, which is characterized by seizures that affect the vocal tract." (PMID 31213517, 2019). "Supporting a regulatory role of Elp4, genomic variants in human Elp4 have been associated with the appearance of centro-temporal spikes in Roland epilepsy, while microdeletions of the same Elongator subunit are associated with language impairment, autism spectrum disorder, and mental retardation." (PMID 34968241, 2020). "The recent report of a role for the gene encoding the transcription factor ELP4 in the development of centrotemporal EEG spikes in rolandic epilepsy further suggests that the common genetic epilepsies can be influenced by genes involved in the regulation of gene expression in brain development." (PMID 21887291, 2011). "Mutations in other Elongator complex subunits, namely, ELP2 and ELP4, have been correlated with neurodevelopmental disabilities and rolandic epilepsy, respectively." (PMID 30477220, 2018). "It has also been reported that Elp4 might contribute to Rolandic epilepsy, although another study could not find a correlation between Elp4 gene and centrotemporal spikes." (PMID 33152999, 2020).
Intellectual disability (6 papers, 2017 to 2023). "Variants in the ELP2 gene are associated with neurodevelopmental (including intellectual) disability while ELP3 variants are associated with ALS, and loss of ELP4 can cause Rolandic epilepsy syndrome and intellectual disability." (PMID 28167615, 2017). "Here, we identify ELP4 and ELP6 variants in patients with developmental delay, epilepsy, intellectual disability, and motor dysfunction." (PMID 35698786, 2022).
epilepsy (5 papers, 2011 to 2022). A brain disorder characterized by episodes of abnormally increased neuronal discharge resulting in transient episodes of sensory or motor neurological dysfunction, or psychic dysfunction. "In a separate study, genes associated with epilepsy-aphasia spectrum, that encode for elongator acetyltransferase complex subunit 4 (ELP4) and sushi-repeat containing protein X-linked 2 (SRPX2), were studied for their potential interactions in BECTS." (PMID 30319421, 2018). "Associations between variants in genes involved in tRNA modifications and some phenotypes have been reported, for example, ELP4 and epilepsy, and IKBKAP and bronchial asthma." (PMID 26416026, 2015). "Interestingly, three other Elongator subunits, ELP2 to ELP4, have each been associated with CNS disorders: ELP2 and ELP4 have been implicated in intellectual development disorders and epilepsy, and ELP3 with amyotrophic lateral sclerosis." (PMID 28167615, 2017).
autism (4 papers, 2011 to 2021). Persistent deficits in social interaction and communication and interaction as well as a markedly restricted repertoire of activity and interest as well as repetitive patterns of behavior. "When we expanded the dataset to include the entire 271 autism susceptibility genes that are expressed in the human amygdala, we found an additional five genes (PHF21A, RNABP17, ELP4, CNKSR2, and NAV2) with altered expression in individuals with ASD." (PMID 32460837, 2020). "Microdeletions including or disrupting the ELP4 gene were also shown in patients with neurodevelopmental disorders including autism spectrum, speech/language disorders, epilepsy, and developmental delay." (PMID 29460221, 2018). "Candidate genes such as BDNF, ELP4, PRRG4, and SLC1A2 have been identified in relation to autism, cognitive/developmental delays, and behavioral problems." (PMID 34970513, 2021).
WAGR syndrome (3 papers, 2017 to 2022). WAGR syndrome (Wilms tumor - aniridia - genitourinary anomalies - intellectual disability mental retardation) is a rare genetic disorder characterized by an unusual complex of congenital developmental abnormalities with intellectual disability, and an increased risk of developing Wilms tumor. "Further research is needed to explore potential mechanisms leading to seizures in patients with WAGR syndrome, as a variety involving the common WAGR genes and SLC1A2 and ELP4 genes have been suggested." (PMID 34970513, 2021).
developmental delay (2 papers, 2021 to 2022). "During routine clinical examination, we identified one individual with two missense variants in ELP4 and two individuals with a missense variant in ELP6 presenting with a global developmental delay and dysmorphic features." (PMID 35698786, 2022).
Nystagmus (2 papers, 2022 to 2024). Rhythmic, involuntary oscillations of one or both eyes related to abnormality in fixation, conjugate gaze, or vestibular mechanisms. "The mutation or deletion of ELP4 can suppress the expression PAX6 which controls eye development, and results in aniridia syndrome characterized by impaired vision and nystagmus." (PMID 35456484, 2022).
arachnoid cyst (1 paper, 2019). Intracranial or spinal cavities containing a cerebrospinal-like fluid, the wall of which is composed of arachnoidal cells. "In this paper, we investigated the association between elongator protein complex 4 (ELP4) rs986527 polymorphism and the occurrence and development of intracranial arachnoid cysts." (PMID 31743616, 2019). "Genotyping of ELP4 rs986527 polymorphism was performed in all intracranial arachnoid cyst patients and healthy controls using genomic DNA extracted from peripheral blood leukocytes." (PMID 31743616, 2019). "In conclusion, our results indicated that ELP4 was associated with pathogenesis of intracranial arachnoid cysts." (PMID 31743616, 2019). "The incidence of polymorphism and clinical symptoms of ELP4 rs986527 in all patients with intracranial arachnoid cysts was studied." (PMID 31743616, 2019). "The relationship between ELP4 rs986527 polymorphism and intracranial arachnoid cysts was studied." (PMID 31743616, 2019).
cataract (1 paper, 2021). Partial or complete opacity of the crystalline lens of one or both eyes that decreases visual acuity and eventually results in blindness. "We had 1 patient (patient 3-I) with a 3′ UTR gene deletion extending to involve ELP4 and DCDC1; she presented with partial iris hypoplasia, cataracts, glaucoma, and a retinal detachment in a surgically naive eye but no reported ARK." (PMID 34101622, 2021).
hepatocellular carcinoma (1 paper, 2022). A malignant tumor that arises from hepatocytes. "Some of the ELP members showed differential roles in various cancers, for example, aberrant expression of Elp3 or Elp4 promoted the migration and invasion of hepatocellular carcinoma cells." (PMID 35223903, 2022).
osteosarcoma (1 paper, 2021). A usually aggressive malignant bone-forming mesenchymal neoplasm, predominantly affecting adolescents and young adults. "Using the Direct Repeat-Green Fluorescence Protein (DR-GFP) assay, knockdown of ELP4 significantly reduced HR efficiency in the osteosarcoma cell line U2OS." (PMID 33803939, 2021).
neurological disorders (3 papers, 2022 to 2025). "ELP4 gene mutations and deletions have been linked to a variety of neurological diseases." (PMID 39822731, 2025). "ELP4 is a subunit of the elongator complex, and its impairment may be related to several neurological disorders." (PMID 39822731, 2025).
cancer (2 papers, 2021 to 2022). A tumor composed of atypical neoplastic, often pleomorphic cells that invade other tissues. "Expression of ELP4 and ELP5 at mRNA level is associated with increased sensitivity to olaparib in GDSC pan-cancer cell lines." (PMID 33803939, 2021). "While ELP4 and ELP5 mRNA expression are associated with olaparib sensitivity from univariate analysis of GDSC pan-cancer cell lines, ELP4 and ELP6 missense variants may contribute to sensitivity to olaparib in the HGSOC cell line TOV2978G." (PMID 33803939, 2021). "We analyzed data from two independent groups of cancer cell lines and identified alterations in additional genes (PUM3, EEF1A1 and ELP4) that potentially increase sensitivity to olaparib." (PMID 33803939, 2021).
neurodevelopmental disorder (2 papers, 2016 to 2018). A behavioral and cognitive disorder with onset during the developmental period that involves impaired or aberrant development of intellectual, motor, or social functions. "Beside RE, there are other neurodevelopmental disorders associated with the CTS trait, such as speech disorder developmental coordination disorder and attention deficit-hyperactivity disorder that could be also linked to Elp4, as in the case of RE." (PMID 27847465, 2016).
ELP4 also shares sentences with these, for which no sentence is quoted: amyotrophic lateral sclerosis (3 papers); autism spectrum disorder (2); Wilms tumor (2); aniridia syndrome (1); Aphasia (1); corneal dystrophy (1); glaucoma (1); ischemic stroke (1); microcephaly (1); Obesity (1); optic nerve hypoplasia (1); optic neuropathies (1); Posterior polar cataract (1); Strabismus (1).